S100A9 (S100 calcium binding protein A9)
Diseases named in the same sentence as S100A9 in open-access papers (continued):
Sharing a sentence is not in itself a finding about the gene and the disease.
cancer (continued). "Previous studies have demonstrated various effects of S100A9 on inflammation in a variety of cells, growth of cancer cells and activation of natural killer (NK) cells." (PMID 32149126, 2020). "S100A8 and S100A9 function as essential factors in inflammation and also exert antitumor or tumorigenic activity depending on the type of cancer." (PMID 32903598, 2020). "Taken together, these results suggest that exosomal S100A9 from G‐MDSCs promotes CAC susceptibility and is involved in enhancing the stemness of cancer cells." (PMID 31559140, 2019). "Although the aberrant expressions of S100A8/S100A9 has reported in a variety of cancer tissues, the functional studies are also necessary to pay more attention." (PMID 31208368, 2019). "Collectively, these results suggest that exosomal S100A9 from G‐MDSCs promotes the stemness of cancer cells and the subsequent development of CRC." (PMID 31559140, 2019). "Next, exosomes from human MDSCs (hM‐Exo) was isolated from MDSCs, and the roles of hM‐Exo and the S100A9 cargo in the stemness of cancer cells were observed." (PMID 31559140, 2019). "It has reported that S100A8/S100A9 forms heterodimers and plays an important role in regulating cells proliferation and apoptosis in some normal and cancer cells." (PMID 31208368, 2019). "Assessment of potential invasion-mediating genes in NFPAs revealed that CM from M2 macrophages displayed increased expression of S100A9, a regulator of inflammation and invasion expressed by cancer cells." (PMID 31040912, 2019). "S100A8 and S100A9, two heterodimer-forming members of the S100 family, aberrantly express in a variety of cancer types." (PMID 31208368, 2019). "S100A9 is constitutively expressed in myeloid cells including granulocytes, monocytes, early-differentiation cells of the myeloid lineage, and cancer cells." (PMID 31620141, 2019). "Infiltrating monocytes/macrophages lead to upregulation of S100A8 and S100A9 expression in cancer cells, which was correlated with elevated metastasis formation in HCC." (PMID 31611871, 2019). "Our previous study, consistent with others, showed that S100A9 in the CRC microenvironment directly contributes to malignancy in CRC cancer cells." (PMID 31620141, 2019). "S100A8-GST and S100A9-GST were incubated with anti-S100A8 and anti-S100A9 neutralising antibodies for 1 h before addition to cancer cell cultures." (PMID 30558665, 2018). "As a classical inflammation-associated cancer for HBV-related HCC, the elevated levels of serum S100A9 were also observed, and its serum levels had a better diagnostic value for identifying extrahepatic metastasis." (PMID 29795379, 2018). "S100A8-GST and S100A9-GST were incubated with respective neutralizing antibodies (anti-S100A8 and anti-S100A9) for 1 h at 37 °C before addition to cancer cells." (PMID 30558665, 2018). "Strong up-regulation of S100A8/S100A9 has also been detected in various human cancers and promotes tumors progression, including gastric, colon, breast, and live cancer." (PMID 30558666, 2018). "Conditioned media from Panc-1, Suit-2 and BxPc3 cancer cell lines caused increased expression of S100A8 and S100A9 proteins in primary human monocytes." (PMID 30558665, 2018). "Recent studies have highlighted S100A8 and S100A9 as having an important role in cancer pathogenesis." (PMID 29955397, 2018). "Calprotectin, a heterodimeric complex of the calcium-binding proteins S100A8 and S100A9, regulates cell cycle progression at G2/M, inhibiting cancer cell migration and invasion, and suppressing tumorigenesis in vitro and in vivo." (PMID 29868478, 2018). "Our results contribute to the demonstration that S100A8 and S100A9 are critical for an efficient proinflammatory process but are also key actors of the development of many chronic inflammatory diseases and cancer." (PMID 29593718, 2018).
cancer (continued). "This is likely a result of colorectal metastatic disease, as S100A8/S100A9 is an important mediator in cancer pathology which induces growth and stimulates metastasis." (PMID 29675023, 2018). "While the roles of s100a8/a9 in mucosal healing have been largely overlooked, s100a8 and s100a9 can promote dermal fibroblast proliferation and can facilitate migration of cancer cells via direct and indirect mechanisms." (PMID 28769105, 2017). "S100A9 has been found mainly up-regulated in different cancers, but, opposite levels were also reported (for detailed references please)." (PMID 29286311, 2017). "In contrast, some of past studies showed that S100A8 and S100A9 protein have inhibitory effects on the proliferation of carcinoma cells and normal fibroblasts by inducing cell apoptosis." (PMID 28637501, 2017). "Decrease in calcium levels upon stimulation was abrogated when S100A8 and S100A9 were knocked down in the cancer cells." (PMID 27086923, 2016). "Granulocytes did not provoke ERK activation to the same extent, consistent with their reduced ability to induce S100a8 and S100a9 expression in cancer cells." (PMID 27086923, 2016). "Because the levels of S100A8 and S100A9 in untreated MC38 and LLC cells were low, we first induced S100A8 and S100A9 expression by stimulating cancer cells with monocyte/macrophage-conditioned medium." (PMID 27086923, 2016). "In the same study, we also found that S100A8 and S100A9 expression in cancer cells was altered by removal of the CD11b+ cells." (PMID 27086923, 2016). "As a calcium- and zinc-binding protein, S100A9 plays an important role in immune suppression of cancer." (PMID 27661117, 2016). "Suppression of S100A8 and S100A9 in cancer cells using short hairpin RNA significantly diminished migration and invasion in culture." (PMID 27086923, 2016). "In this study, we report that monocytes/macrophages induce S100a8 and S100a9 messenger RNA (mRNA) expression in cancer cells in an extracellular signal-related kinase (ERK)-dependent manner." (PMID 27086923, 2016). "S100A9-mediated increase of IL-6 expression was partly through the cross-talk between cancer and myeloid cells." (PMID 26315114, 2015). "Proinflammatory molecules such as IL-17, CCL20, S100A8, S100A9, and S100A8/A9 have been shown to be implicated in many types of cancer." (PMID 26273651, 2015). "Both S100A9-bearing TW-2.6-CM and recS100A9 protein were used to study the extracellular role of S100A9 in cancer cells and 2 stromal cell types, monocytes and endothelial cells (EC)." (PMID 26315114, 2015). "It indicates that there is a direct link between the expression of IL-17, CCL20, telomerase, S100A8, and S100A9 in the fibrotic condition and the progression towards cancer." (PMID 26273651, 2015). "An increasing amount of data indicate that S100A8 as well as S100A9 homodimers are important regulators of inflammation and cancer, exhibiting strong pro-inflammatory activity in various mouse models of diseases." (PMID 23626736, 2013). "Abnormal expressions of S100 proteins, including S100A8 and S100A9, were over-expressed in a variety of different cancers, such as gastric, lung, breast, liver, pancreatic and squamous esophageal carcinomas." (PMID 23637971, 2013). "Correlation among S100A9 expression, clinicopathological features and patient prognosis varies in different cancer types." (PMID 22838504, 2012). "S100A8 and S100A9 are often co-expressed as a complex, suggesting a common mechanism of transcriptional regulation in inflammatory diseases and cancers." (PMID 22139384, 2012). "S100A8 and S100A9 proteins, usually occurring as the heterodimeric complex, calprotectin, are changed significantly at the early stages of cancer." (PMID 23166536, 2012). "We focused our study on S100A8 and its heterodimeric partner S100A9 because of their role in inflammation and cancer, and their prominence among ZD-induced proinflammation markers in ZD:Cox-2−/− forestomach." (PMID 20857495, 2011).
cancer (continued). "Increased levels of S100A8 and S100A9 have been detected in various human cancers, being abundantly expressed in neoplastic cells and also in infiltrating immune cells." (PMID 19440546, 2009). "The most recent data on this topic have shown that MSLN can also drive macrophage polarization towards an immunosuppressive phenotype characterized by the secretion of VEGFA, ARG1, and S100A9, thereby stimulating cancer cell growth and weakening the immune response." (PMID 41335396, 2025). "In the osteoblasts_Gapd2 subpopulation, pathways such as proteoglycans in cancer (Col1a1, Col1a2, Hcls1, Hif1a, Stat3, Vav1), IL-17 signaling (Mmp13, Mmp3, S100a9, Ccl7, Cebpb), and ECM–receptor interaction (Col11a2, Col1a1, Ibsp, and Tnn) were activated (p < 0.05)." (PMID 41459160, 2025). "HMGB1, HSP90, S100A9, and ATP were emphasized as the expression DAMPs in cancer patient serum." (PMID 39768997, 2024). "Blocking the effect of S100A8 and/or S100A9 in cancer-related inflammation could potentially relieve myeloid-mediated immune suppression and synergize with other cancer immunotherapies." (PMID 39497822, 2024). "Moreover, elevated levels of S100A8 and S100A9 expression correlate with diminished disease-free survival rates in cancer patients." (PMID 39768997, 2024). "High expression of S100A9 favors M2 polarization of macrophages, resulting in cancer progression." (PMID 38713229, 2024). "Previously published works into the role of S100A8, S100A9 or heterodimer S100A8/A9 in cancer." (PMID 39497822, 2024). "S100A8 and S100A9/Cd93 were major communication axes within Cancer-B1/2/3-TME." (PMID 39695088, 2024). "The high methylation in the promoter region inhibits the expression of S100A9, which may influence S100A9-targeted drug resistance and cancer progression in female patients." (PMID 39175079, 2024). "Some of these potential proteins (COL12A1, THBS2, S100A8, and S100A9) were reported to associate with other cancers and non-malignant diseases, which limited the clinical validity of the potential proteins in CRC." (PMID 38302471, 2024). "Similarly, the GDS4382 dataset showed significantly higher expression of S100A8 and S100A9 in cancer tissues compared to corresponding paracancerous tissues (P<0.05)." (PMID 38817853, 2024). "We also explored the predictive efficacy of the four proteins (COL12A1, THBS2, S100A8, and S100A9) in multi-cancer cohort composed of 115 plasma samples from 95 patients with treatment-naive patients with various cancer types and 20 HCs, and two public cohorts related to the non-malignant diseases." (PMID 38302471, 2024). "Furthermore, the percentage of weight loss within 6 months before cancer diagnosis in PC patients positively correlated with serum levels of S100A8 (r = 0.33, P < 0.001), S100A9 (r = 0.30, P < 0.001), and S100A8/A9 (r = 0.24, P = 0.004)." (PMID 37280516, 2023). "Indeed, iASPP-deficient cells increased expression of inflammatory cytokines S100a8 and S100a9, which are also expressed by apoptotic cancer cells and can promote metastasis." (PMID 36746936, 2023). "Additionally, S100A8 and S100A9 are considered biomarkers of poor prognosis in inflammatory and metabolic diseases as well as some types of cancer." (PMID 38049858, 2023). "Therefore, differentiating MDSCs from other S100A9-expressing cells under cancer-induced inflammatory conditions is difficult." (PMID 37238964, 2023). "Such connection between S100A9, cancer stem cells and therapeutic resistance might involve an underlying plasticity highly influenced by the microenvironment." (PMID 36652782, 2023). "Given that the binding of S100A9 to RAGE in the cancer cell is the trigger to the activation of nuclear factor kappa B (NF-κB) signaling and JunB, which underlies the resistance mechanism to radiotherapy, this therapeutic approach paradoxically desensitizes metastatic cells to it." (PMID 36652782, 2023). "S100A9 has been found to be a protein that bridges inflammation and cancer." (PMID 37691944, 2023).
cancer (continued). "Notably, we detected several critical regulating proteins associated with cancer processes, such as CAMP, MMP9, the S100 family (100A8, S100A9, S100A12), and PRTN3, among the proteins with the most significant increases." (PMID 37231509, 2023). "Altogether, these findings suggest an intriguing working model in which loss of Brca1 in cancer cells results in upregulation of S100A9, which, in turn, not only positively regulates S100A9 expression in cancer cells but also acts extracellularly to induce MDSC accumulation." (PMID 35304461, 2022). "Similarly, analysis of cancer cells with activated NF-κB signaling (mCherry+/ GFP+) after irradiation in vivo confirmed their dependency on S100A9." (PMID 35411077, 2022). "Interestingly, this signature was also present in cancer cells plated on brain organotypic cultures 31, denoting S100A9 as the top upregulated gene." (PMID 35411077, 2022). "However, at high intracellular concentrations, S100A9 induces a reduction in cancer cell invasion capacity by regulating the epithelial–mesenchymal transition–the mesenchymal–epithelial transition (EMT–MET) signaling cascades." (PMID 35123499, 2022). "Our in vitro and ex vivo radioresistance paradigms might involve different mechanisms mediating the induction of S100A9 in cancer cells (that is, acquisition of stem cell properties versus the influence of the microenvironment)." (PMID 35411077, 2022). "Based on previous studies and our findings, we speculated that S100A9 might be an important factor in cancer development and cisplatin-resistance of HPC." (PMID 36072966, 2022). "Thus, our data suggest that S100A9 expression is induced in cancer cells under specific contexts correlating with the acquisition of radioresistance." (PMID 35411077, 2022). "CCL22 is found in a broad range of human cancers with potent pro-tumoral functions, while S100A8 and S100A9 are expressed by MDSCs in human CRC patients, are associated with the recruitment and immunosuppressive functions of MDSCs, and correlate with advanced CRC." (PMID 35658010, 2022). "S100A9 was elevated in inflammation and various human cancers." (PMID 35123499, 2022). "Lately, S100A8 and S100A9 have been increasingly used as in vivo imaging biomarkers in cancer." (PMID 35741108, 2022). "We first identified a cell surface marker from S100A9+ cancer cells." (PMID 35411077, 2022). "Overall, our data suggest that the induction of S100A9 in brain metastasis might be the consequence of an inflammatory response initiated by the direct contact between reactive astrocytes and cancer cells." (PMID 35411077, 2022). "Because interferon-α and TGF-α were not included in our unbiased approach, we interrogated whether any of them induced S100A9 expression in cancer cells and concluded that only TGF-α did so." (PMID 35411077, 2022). "A substantial body of evidence highlights the importance of S100A9 in cancer." (PMID 33963011, 2021). "Experimental data indicated that S100A9 presents abundant expression in various inflammation-associated human cancers, no doubt including CRC." (PMID 34093546, 2021). "Secondly, elevated level of S100A8 and S100A9 observed in cancer and other inflammatory diseases." (PMID 34372836, 2021). "Importantly, patients with high S100A9 expression or a high monocyte count had significantly reduced cancer-specific survival compared to patients with low expression or low count." (PMID 34067757, 2021). "Considering that interferon regulatory factor‐7 (IRF7) regulates the development of G‐MDSC through S100A9 gene transcription in cancer 19 and modulates progression of EAE in mice, we also compared relative expression of IRF7 mRNA in PBMC of MS patients before and after MPPT." (PMID 33094923, 2020). "However, little is known about the mechanism that regulates S100A8/S100A9 co-expression in cancer cells." (PMID 31208368, 2019). "On the one hand, exosomal S100A9 from G‐MDSCs enhances cancer cell stemness." (PMID 31559140, 2019).
cancer (continued). "The upregulated S100A9 expression in MC‐38 cells could promote invasion and migration, which are related to cancer stemness." (PMID 31559140, 2019). "Our results also revealed that the inactivation of YAP and the induction of S100A8/S100A9 could significantly increase the survival of cancer cells, which may also be a mechanism by which cancer cells overcome anoikis during metastasis." (PMID 31208368, 2019). "Finally, screening of oligonucleotide microarrays to identify S100A9-related transcripts detected several cancer-related genes whose expression was upregulated or downregulated by S100A9 knockdown." (PMID 31055998, 2019). "To test the hypothesis that the S100A9+ MDSC-derived macrophages can protect cancer cells from EGFR-TKI killing, we isolated CD14+ monocytes from PBMCs and induce them into macrophages (monocytes-derived macrophages, MDMs)." (PMID 29484139, 2018). "Growing evidences show that chronic inflammation greatly increases the risk of tumorigenesis, we next concern whether the progression of “inflammation–cancer link” in CAC mouse model will be suppressed by blocking the pro-inflammatory molecule S100a9." (PMID 29326691, 2017). "Based on our bioinformatics analysis of Annexin A1 associated proteins and the literature on the critical roles of Annexin A1, namely, S100A9 and Vimentin in cancer invasion and metastasis, Annexin A1/Vimentin/S100A9 was selected interaction interactions for further study." (PMID 28355254, 2017). "S100A9 is a calcium binding protein with multiple ligands and post-translation modifications that is involved in inflammatory events and the initial development of the cancer." (PMID 29286311, 2017). "Neutrophils may be mobilized into liver premetastatic niches by S100A8 and S100A9 or chemokines and cytokines secreted by activated macrophages, endothelial cells, or cancer cells." (PMID 28969005, 2017). "S100A8 and S100A9 expression in cancer cells was critical for invasion by liver metastases." (PMID 27086923, 2016). "Researches have provided valuable insights into the tumorigenesis of S100A9 in some cancers." (PMID 27020242, 2016). "Moreover, given that metastases can and often do derive from other metastases, this makes the S100A8- and S100A9-mediated invasive capacity of cancer cells more ominous." (PMID 27086923, 2016). "S100A9 is a member of the S100 family and is overexpressed in various forms of cancer." (PMID 27600085, 2016). "Moreover, S100A8 and S100A9 were found to be upregulated in defined parts of dysplasia/cancer regions and in the invasion nests in SCC sections." (PMID 25811984, 2015). "However in cancer patients, S100A9 serum levels were reported to be significantly lower in nano- to μg/ml range, despite being higher than those of healthy controls." (PMID 26431492, 2015). "The overexpression of S100A8 and S100A9 in cancer cells was also confirmed by immunohistochemistry." (PMID 25673070, 2015). "Furthermore, functions of CHI3L1 and S100A9 in cancer cells are also inversely correlated each other." (PMID 26431492, 2015). "Therefore, there is a direct link between the expression of IL-17, CCL20, telomerase, S100A8, and S100A9 in the fibrotic condition and the progression towards cancer." (PMID 26273651, 2015). "Thus, we would like to propose S100A9 as a pertinent target for the development of novel anti-cancer treatments." (PMID 23667563, 2013). "In addition, increased expression levels of S100A8 and S100A9 have been detected in various human cancers in recent years." (PMID 24083576, 2013). "Therefore exogenous or endogenous stimuli which induce S100A8 and S100A9 during developing cancers have the potential to exacerbate such disease states by augmenting the number or activation of MDSCs." (PMID 22946998, 2012). "Also, these cells secrete S100A9, which has a pro-survival effect on cancer cells." (PMID 38673949, 2024).